SNORA16B (small nucleolar RNA, H/ACA box 16B)
Synonyms: U98b
Gene: Small nucleolar RNA gene on chromosome 1 (212,352,816 to 212,352,950, forward strand). Ensembl gene ENSG00000201544.
Gene Ontology:
Biological process: RNA processing
Cellular component: nucleolus
Homologues: Orthologues: chimpanzee SNORA16B (97% identical), macaque SNORA16B (95% identical). Paralogues in human: SNORA16A (87% identical).